RPS6 (ribosomal protein S6)
Diseases named in the same sentence as RPS6 in open-access papers (continued):
Sharing a sentence is not in itself a finding about the gene and the disease.
tumor (continued). "An additional major difference between tumours and cell lines involved phospho-RPS6, an indicator of mTOR activity." (PMID 15956968, 2005). "Phosphorylated RPS6 was undetectable in both tumours and normal kidney, despite usually abundant levels of total RPS6 protein." (PMID 15956968, 2005). "Our observation of RPS6KB1 and RPS6 hypophosphorylation could also relate to DNA damage since DNA damage suppresses S6K1-mediated RPS6 phosphorylation in various tumour cells." (PMID 41253884, 2025). "RPL4, RPLP0, and RPS6 are closely related to tumor growth and cell cycle control; this relationship indicates that they may contribute to the transcriptomic stability and survival of TICs." (PMID 40862733, 2025). "Indeed, we found that MLN0128 treatment effectively suppressed c-MYC/MCL1/RictorKOTsc2KO tumor growth, and it was more effective than the p70S6K/RPS6 inhibitor everolimus." (PMID 39325536, 2024). "Moreover, IHC assays showed that p-rpS6 was significantly reduced in tumor cells from mice treated with metformin for 24 days (p < 0.05)." (PMID 39026155, 2024). "Growth factors, tumor promoters, and mitogens are inducers of RPS6 phosphorylation." (PMID 39621600, 2024). "It has been established that p70S6K/RPS6 regulates tumor metabolism, such as de novo lipogenesis." (PMID 39325536, 2024). "We assume that an upregulation of RPS6 in LSCC cells could be consistent with a boost of protein synthesis required to shape tumor-related proteome." (PMID 36675308, 2023). "Therefore, we used antibodies recognizing phosphorylated RPS6 (pS6) as a tool for assessing the activity of the mTORC1-S6K pathway in pre- and post-treatment tumor samples in situ." (PMID 36147916, 2022). "Similarly, the human HCC cell line, SK-HEP-1, expresses a low level of p-RPS6 and is more vulnerable to TRAIL-induced apoptosis than other tumor cells that express a high level of p-RPS6." (PMID 35008473, 2021). "Inversely, transient overexpression of RPS6 enhanced the tumor-sphere formation of these cells." (PMID 35008473, 2021). "RPS6 phosphorylation (Ser235/236) was predominantly expressed in the peri-necrosis area and peri-vascular area, compared with the cellular tumor area." (PMID 34831193, 2021). "To confirm this, we performed IHC on the tumours to look for activation of downstream effectors of both of these pathways—phosphorylated ribosomal protein S6 and phosphorylated 4EBP1 for the PI3K/AKT/mTOR pathway, and phosphorylated ERK1/2 for the Ras/Raf/MEK/ERK pathway." (PMID 33053751, 2020). "RPS6 knockdown may influences tumor cell proliferation, migration, and invasion, and induces cell cycle arrest." (PMID 32862831, 2020). "Hence, these findings also explain the inhibition of tumor invasion and migration ability upon RPS6 knockdown." (PMID 32862831, 2020). "Furthermore, the pivotal role of rpS6 phosphorylation in tumor formation is consistent with our observation that DRAM1 inhibits rpS6 phosphorylation and act as a tumor suppressor." (PMID 30902093, 2019). "Since a faster rate of ATP production is essential to support cancer growth and metastasis, the present study identified the effect of STC1-overexpression on reducing energy metabolism, leading to an activation of AMPK pathway but an inhibition of p70S6K/p-rpS6 signaling to reduce tumor growth." (PMID 29467934, 2018). "Collectively, these results imply that the tumorigenic effect of myr-Akt in β-cells is mediated by rpS6 phosphorylation and is accompanied by augmented cell proliferation at the onset of the tumor progression, with p27 as a potential effector downstream of Akt and rpS6." (PMID 26919188, 2016).
tumor (continued). "Phosphorylation of ribosomal protein S6 on either Ser235/236 or Ser240/244 was consistently and significantly correlated with favorable prognosis, although with differences depending on the tumor site." (PMID 27119232, 2016). "Interestingly, decreased phosphorylation of RPS6 has been correlated with decreased tumor angiogenesis." (PMID 27618721, 2016). "Elevated p-rpS6 expression levels were observed in the tumor tissue of 125 patients (21%)." (PMID 26506236, 2016). "Despite the width of the deletion, 54.2% of ia2 tumors are specifically represented by zMPNSTs, suggesting that the rps6 gene haploinsufficiency might be the initial driver biasing the tumor histotype." (PMID 26695815, 2015). "Furthermore, in these patients phosphorylation of ribosomal protein s6 was significantly correlated with tumor stage and grade." (PMID 22685542, 2012). "Thus reduced RpS6 expression results in tissue overgrowth, consistent with RpS6 having a tumour suppressor like function." (PMID 22194697, 2011). "Interestingly, phospho-RPS6 was markedly reduced in tumours, suggesting that mTOR activity was lower than observed in cell lines." (PMID 15956968, 2005). "Here, we used volumetric 3-dimensional (3D) imaging to explore the inner landscape of clinical UTUC biopsies, without sectioning, revealing that 3D analysis of phosphorylated ribosomal protein S6 (pS6) could predict tumor grade and prognosis with improved accuracy." (PMID 39133649, 2024). "Furthermore, the interleukin 6 (IL6)-induced tumor sphere formation was reduced by RPS6-KD." (PMID 35008473, 2021). "In addition, hypoxia is an important inducer of neoangiogenesis, and activated RPS6 may play an important role in the crosstalk between endothelial cells and tumor cells in the tumor microenvironment." (PMID 35008473, 2021). "Lai and colleagues showed that 17 of 28 zebrafish heterozygous mutant lines characterized by the loss of function of 28 different rp genes (rps6 was not included) developed zMPNSTs, and suggested that many rp genes act as haploinsufficient tumor suppressors in fish." (PMID 26695815, 2015). "Thus, differences in RPS6 phosphorylation between tumours and cell lines may be a result of different growth rates or of cell–cell interaction." (PMID 15956968, 2005). "Together, these results show that LY-2584702 and BMS-777607 are well tolerated when given orally on a dosing schedule that effectively inhibits rpS6 and reduces GBM tumor size." (PMID 39087397, 2024). "The concordance of studies on the expression of p-RPS6 in OED and OSCC suggests the involvement of the deregulated Akt/mTOR pathway in the early events of tumor progression and the pathogenesis of OSCC." (PMID 38370876, 2024). "Conversely, we demonstrate that overexpression of KHKC in KPC cells enhances KRAS downstream pathway, while KHKA overexpression acts as a tumor suppressor by blocking the phosphorylation of ERK1/2 and decreasing RPS6 activation." (PMID 37559908, 2023). "The C2-tumor cluster had high autophagy (ATG5, MAP1LC3B), high plasticity (SOX4, CD164) and low mTORC1 activity (RPS6, MLST8), characteristics of early paligenosis (stages 1-2)." (PMID 36788228, 2023). "The HPA database shows that the proteins of POL2B, RPS6 and RPL23A are highly expressed in HCC tissues, and are expected to be molecular targets for anti-tumor." (PMID 36439183, 2022). "Since the tumor sphere formation and the expression of Nestin and SOX2 are the characteristics of GSCs, these results suggest that RPS6 plays critical roles in the development and maintenance of GSCs." (PMID 35008473, 2021). "RPS6-KD reduced p-JAK2 and p-STAT3 and suppressed the tumor sphere formation, a characteristic of GSCs, of GBM cells in vitro." (PMID 35008473, 2021).
tumor (continued). "Importantly, there were significant positive associations between expression of Ki67 and P rpS6, SDH, eIF4A and ATP5A, consistent with a link between or co-regulation of the processes of protein synthesis, mitochondrial function and enhanced cell growth in MpM tumours." (PMID 34389715, 2021). "To ascertain if the expression levels of RPS6KB1, RPS6 and IRS-1 proteins varied based on stage of CMM, we used 42 tumor samples (stage I–IV) and 5 normal skin tissues." (PMID 33082316, 2020). "In vivo, DHA inhibited the tumor growth of ESCC patient-derived xenografts and weakened p-mTOR, p-p70S6K, and p-RPS6 expression in tumor tissues." (PMID 33658929, 2020). "Incubation under hypoxic conditions (0.1% oxygen), as can be found in the tumour microenvironment, triggered HIF-1α stabilisation and induced DDIT4 gene expression and protein with decreased phosphorylation of RPS6 as evidence for mTORC1 inhibition." (PMID 30745581, 2019). "RPS6, RPS19 and RPS25 helps in the transcription initiation of viral genes while RPL5 and RPL11 acts as tumor suppressors by degrading the mRNA of c-myc, through RNA induced silencing complex (RISC)." (PMID 29568375, 2018). "When activated by sCPE, phosphorylated RPS6 contributed to decrease-, and when pharmacologically inhibited, dephosphorylated RPS6 resulted in an increase of GTP-bound Rac1, therefore affecting tumor cell motility." (PMID 28978054, 2017). "Then we examined the effect of AZD3463 on the PI3K/AKT/mTOR signaling in the tumor tissues and found that AZD3463 efficiently blocked Akt and RPS6 phosphorylation and induced the cleavage of PARP, caspase 3, and LC3 A/BΙΙ in vivo." (PMID 26786851, 2016). "The expressions of t-rpS6 and p-rpS6 (Ser235/236) were immunohistochemically detected in 316 NSCLC tumor tissues and 82 adjacent normal controls." (PMID 26490682, 2015). "Both of t-rpS6 and p-rpS6 were abundantly accumulated in the cytoplasm of NSCLC cells, but less frequently found in non-tumor controls." (PMID 26490682, 2015). "Apparent differences between primary tumours and cell lines suggest that it would be particularly useful to examine tumours pre- and post-treatment with phospho-specific antibodies to ERK, AKT and RPS6 (or S6K)." (PMID 15956968, 2005). "Meanwhile, the emergence of RUNX1 mutation, upregulations of genes expression (RPS27A, RPS6, UBA52, RACK1) on tumor cells, and increased frequencies of T and NK cells with TIGIT, CTLA4, and LAG3 expression were observed after midostaurin treatment, predicting the disease progression of this patient." (PMID 37638009, 2023). "It would thus not be surprising that stromal endoglin and tumor TGFβ receptor cooperate in trans to potentiate AKT/RPS6 signaling and protein synthesis in AML cells." (PMID 37819151, 2023). "Importantly, EGFR, MET, EPHA2, MAPK1, MAPK3, and RPS6 kinase pathways were strongly dependent on FLCN in RPTEC and also strongly respond to FLCN reconstitution in this BHD tumor cell line, as highlighted in the UOK257 INKA rankings in orange." (PMID 35863698, 2022). "Moreover, the activity of mTOR in tumor was promoted by BO treatment as indicated by the phosphorylation of 4E-binding protein 1 (4E-BP1) and ribosomal protein S6, and hyper-autophagy was consequently restrained." (PMID 34658867, 2021). "MiR‐152‐3p might serve as a tumor suppressor in human BC cells via negatively regulating PIK3CA expression to inhibit the activation of AKT and RPS6, leading to suppression of BC cell proliferation (Ge, Wang, Kong, Gao, & Sun, 2017)." (PMID 32124558, 2020). "Furthermore, p-rpS6, p-e-IF4E, p-ATM, and p-DNA-PKcs expression was significantly attenuated in tumor cells after RT + BEZ235 + mBEZ235 treatment when compared with those after RT + BEZ235 treatment." (PMID 31430901, 2019).
tumor (continued). "Exposure of LuCaP 136 tumor-bearing mice to ganetespib and biomarker analysis after 24 or 48 hours paralleled the in vitro biomarker changes including decreased AR, p-AKT, and p-RPS6 and increased HSP70." (PMID 30467317, 2018). "In this retrospective analysis of samples of the OSAG 101-BSA-05 trial, we investigated histological subgroups based on necrosis and hypoxia as markers for a nutrient-deprived tumor microenvironment as well as for phosphorylation of PRAS40 and RPS6 as downstream markers of EGFR signaling." (PMID 30129426, 2018). "Indeed, we observed activated AKT/mTOR signaling in the graft tumor (indicated by phosphorylated AKT, S6K, RPS6)." (PMID 29755689, 2018). "In agreement with the mechanistic findings in vitro, IHC analysis of tumor tissues demonstrated that combined treatment with RAD001 and AZD6244 resulted in greater inhibition of Ki-67, p-RPS6, p-Erk1/2, and p-4E-BP1 compared with the monotherapy and control groups." (PMID 28212559, 2017). "However, all tumor samples were positive for phospho-4E-binding protein 1 (p4E-BP1) and phospho-ribosomal protein S6 (pS6RP), which are targets of the mammalian target of rapamycin (mTOR) pathway." (PMID 25644510, 2015). "Another striking difference was the absence of RPS6 phosphorylation in any of the tumour/normal samples despite easily detectable total RPS6 protein." (PMID 15956968, 2005). "To determine whether upregulated PEPCK1 enhances mTOR/TOR signaling and thus promotes tumor growth under HDS conditions, we assessed mTOR/TOR signaling activity using pS6 antibody, a specific antibody against phosphorylated Ribosomal protein S6 (RpS6), in tumor cells." (PMID 39261338, 2024). "Interestingly, WDR59 and RICTOR KOs showed strong decrease in rpS6 phosphorylation levels, compared with non-targeting tumor samples." (PMID 34031411, 2021). "Of note, the tumor revealed a strong immunohistochemical expression of not only mTOR but also its two main target proteins of the mTOR complex 1 by use of phosphorylation-specific antibodies against the active forms of the proteins, i.e., p‐4EBP1 and p‐RPS6." (PMID 31309284, 2020). "In another model (mouse tumour xenograft model), the induced deletion of ERK5, significantly reduced tumour volume and vascular density, that were mediated by the pro-proliferative and pro-survival factors RSK (p90 ribosomal S6 kinase) and rpS6 (ribosomal protein)." (PMID 26404379, 2015). "Importantly, the central functional role of rpS6 opens up the possibility to exploit the measurement of rpS6 expression levels as a predictive biomarker that prognosticates whether a tumor will respond to pharmaceutical mTOR inhibition or not." (PMID 26506236, 2016).
cancer (81 papers, 2012 to 2026). A tumor composed of atypical neoplastic, often pleomorphic cells that invade other tissues. "Hepatocytes in Rps6-deficient livers also die resulting in small, abnormal livers that are forced to regenerate and predisposed to develop cancer." (PMID 36656901, 2023). "The overexpression of RPS6 has been implicated in intrinsic or acquired drug resistance of cancer cells (see Section 3.2.4." (PMID 35008473, 2021). "In fact, activation of the mTOR/RPS6 pathway has been associated with cancer cell survival, inflammation, and neoangiogenesis through various upstream regulators." (PMID 35008473, 2021). "Previous studies have suggested that RPS6 may be associated with regulating cancer cell proliferation, and its phosphorylation is primarily upregulated by the PI3 K/AKT/mTORC1/S6 K pathway." (PMID 41170411, 2025). "We find RpS6 remains highly expressed when Pxt is lost, suggesting loss of Pxt during Drosophila oogenesis results in nucleolar changes distinct from those in cancer cells due to aspirin treatment." (PMID 36875757, 2023). "High levels of p-RPS6 and low levels of p-AMPKα have been reported to be associated with gastric tumor progression and to be independent predictors of patient survival after resection of primary cancer." (PMID 35008473, 2021). "Additionally, the regulation of PTEN, RPS6 and other relevant cancer-linked markers by CIGB-300 treatment provides new clues about how CIGB-300 could modulate several signaling pathways in this cell model." (PMID 36672551, 2022). "Subjects with high expression of RACK1 & RPS6 were significantly associated with reduced overall (OS), disease-free (DFS), and cancer-specific survival (CSS) (p < 0.001)." (PMID 42058466, 2026). "Elevated expression of RPS6 has been found in many cancers, and research using RPS6-knock-down mouse models has demonstrated a reduction in the proliferation of cancer cell lines." (PMID 41170411, 2025). "Ribosomal protein S6 (p-S6) and the p21 protein (p21) are two proteins that play central roles in other cancers." (PMID 38673889, 2024). "In the signal transduction pathways such as mTOR and PI3K/Akt, mTORC1 further activates RPS6 through phosphorylation of the p70 ribosomal protein S6 kinase to promote protein synthesis for cancer cell growth." (PMID 39621600, 2024). "Multiple studies demonstrated that selective PIM inhibitors reduce phosphorylation levels of ribosomal protein S6 and thus, modulate the translation potential of numerous cancer cell lines." (PMID 37943821, 2023). "It is also known as a proto‐oncogene, whose expression is linked to anti‐apoptotic functions in several types of cancer, including AML, through the activation of AKT/mTORC1/RPS6 signaling." (PMID 37819151, 2023). "It has been reported that siRNA-based knockdown of RPS6 was sufficient to reduce the viability of TNBC cells, suggesting RPS6 as a potential target for treating cancer." (PMID 36358633, 2022). "RPS6 overexpression contributes to metastasis of cancers since it enhances cancer cell migration together with upregulation of epithelial–mesenchymal transition (EMT) markers." (PMID 36364072, 2022). "eIF4E activation appears to be a critical event for Akt-mediated cancer development, whereas the activation of S6K downstream ribosomal protein S6 (rpS6) is dispensable for it." (PMID 36180910, 2022). "A previous study reported that many lncRNAs, that bind to the ribosomal protein S6 in cancer cells, promote HCC progression by regulating cell proliferation and migration, and their levels are correlated with poor prognosis in HCC patients." (PMID 34671598, 2021). "RPS6 or its phosphorylation has been proposed as an alternative target to treat cancer types with high levels of RPS6." (PMID 35008473, 2021). "Further studies will be necessary to reveal the role of RPS6 stability in the combinatorial PKI therapies against cancer." (PMID 35008473, 2021).